IL1B (interleukin 1 beta)
Diseases named in the same sentence as IL1B in open-access papers (continued):
Sharing a sentence is not in itself a finding about the gene and the disease.
infection (continued). "Immunoblot analysis showed that overexpression of SIK1 via ad-SIK1 infection increased SIK1 protein levels in C28/I2 cells under IL-1β treatment for 24 h." (PMID 40059873, 2025). "Numerical correlations observed for pre-infection cytokines measured in plasma (IL-1β, TNF-α, IL-6, IL-10, IFN-γ and TGF-β) and viral loads in brain, lungs and heart for animals from all the groups of the experiment." (PMID 40969767, 2025). "At every time point, significantly lower levels of IL-1β were released from NLRP11∆N_LRR macrophages than their WT counterparts, indicating that NLRP11 is required for IL-1β release even early during infection." (PMID 40272180, 2025). "The control group displayed low expression of inflammatory cytokines, whereas infection significantly upregulated genes such as IL-1β, TNF-α, NF-κB p65, INF-γ, and IL-10 (p < 0.01)." (PMID 41030551, 2025). "Infection of PBECs with RVA16 at MOI 1 for 48 h.p.i resulted in the upregulation (> twofold) of IL-1β and IL-13 expression in PBEC donor cells." (PMID 40916026, 2025). "This complex drives the maturation and release of inflammatory cytokines such as IL-1β and IL-18, which promote further immune activation and recruit additional immune cells to the site of injury or infection." (PMID 40688353, 2025). "IL-1β production is triggered early in infection, acting like a danger signal to initiate the inflammatory response." (PMID 40281973, 2025). "The NLRP3 inflammasome is composed of NLRP3, ASC, and pro-caspase-1, regulating the activation of caspase-1 and following the release of IL-1β and IL-18 from innate immune cells during infection or damage." (PMID 40872501, 2025). "Since hsa-miR-3925-5p has a high coding number and currently available research data on it are limited, we focused on analyzing the potential role of the miR-34a-3p/TNF and miR-190a-3p/IL1B axes in the immune response process following DCs infection with M.tb." (PMID 40725488, 2025). "In vivo and in murine organoids, the bladder mounts a rapid pro-inflammatory response to infection, including production of IL1β, IL-6, IL-8 (CXCL8), and TNF104,105." (PMID 40766562, 2025). "Infection of PNEs with RV-A16 at MOI 0.01 or MOI 1 for 24 h resulted in the upregulation (> twofold) of 6 cytokines (IL-1β, IL-1α, IFN-γ, I-309, TNF-α and IL-11)." (PMID 40916026, 2025). "As the infection or inflammation progresses, fetal leukocytes begin to infiltrate, resulting in elevated concentrations of pro-inflammatory cytokines such as IL-1β, IL-4, IL-6, and IL-8." (PMID 40640885, 2025). "Pre-incubation with either HCMV variant for 24 h or 72 h before infection with A. fumigatus significantly and time-dependently suppressed gene expression and secretion of key cytokines such as CXCL8, VEGFA, IL-1α, IL-1β, IFN-γ, and TNF-α." (PMID 40980889, 2025). "In our study, PRRSV infection led to an increase in IL-1β secretion in PAMs at the late infection stage (24 hpi), in lines with the time point of p38 MAPK signaling activation, confirming that PRRSV infection induces a delayed antiviral inflammatory response." (PMID 40919196, 2025). "Infection with G. parasuis elicits a pronounced inflammatory response, characterised by elevated levels of IL-1β, IL-6, TNF-α, and IL-17, which collectively contribute to tissue damage and systemic inflammation." (PMID 40665414, 2025). "On the third day of infection, IL-1β was more significantly increased in the H9N2-infected group than in the other test groups in the in vivo test." (PMID 40218416, 2025). "Consistently, IHC analysis of HN12 tumor tissues isolated from the NSG xenograft mouse models subjected to mock, wtVSV or VSV-S infection revealed significantly elevated levels of IL-1β and p-MLKL in both wtVSV- and VSV-S-infected groups." (PMID 39789615, 2025). "Protein abundance of TNF-α, IL-1β, and IL-6 increased at 24 h after infection, consistent with mRNA abundance." (PMID 40663568, 2025).
infection (continued). "A strong pro-inflammatory cytokine, interleukin-1β (IL-1β), plays a pivotal role in the host defense against infection and tissue damage." (PMID 40869065, 2025). "Compared with those in the WT infection group, the expression levels of common proinflammatory factors in the ΔL-lectin group were significantly lower, including IFNγ, IL1β, IL6, IL8, and TNFα." (PMID 40076391, 2025). "We found that Tnf-α, Il-1β, and Il-18 were markedly upregulated in liver tissue, especially in the early phase of infection, supporting a role for robust local inflammation in mediating hepatocellular injury." (PMID 40892762, 2025). "Another study demonstrated that neutrophil‐derived IL‐1β drives epithelial cell extrusion, a process observed during the later stages of infection in the EMF model." (PMID 39807570, 2025). "In contrast, the spleen displayed suppressed expression of Il-1β and Il-18 throughout the course of infection, despite demonstrating biochemical markers of injury." (PMID 40892762, 2025). "IL-1β is a potent pro-inflammatory cytokine that plays a critical role in the host’s defense response to infection and injury." (PMID 40218416, 2025). "Experimental infection markedly elevated IL-1β and IFN-γ and thereby sustained mucosal inflammation that compromised intestinal barrier integrity." (PMID 40941293, 2025). "Enzyme-linked immunosorbent assay (ELISA) demonstrated a significant and sustained increase in circulating IL-1β and IL-18 levels during 5–14 days post-infection (dpi), consistent with a systemic inflammatory response." (PMID 41334910, 2025). "After infection, the expression levels of Il10, Tnfa, Il1b and Il6 increased significantly in both young and aged mice at 4 dpi, peaking at 7 dpi." (PMID 41145556, 2025). "SARS-CoV-2 spike protein at 12 μg/ml concentration showed mild induction of IL-1β mRNA expression with slightly higher levels in infection group compared to vaccination group." (PMID 40329195, 2025). "In this study, we demonstrate that infection of human N/TERT-1 immortalized keratinocytes by Staphylococcus aureus induces IL-1β processing independently of the classical inflammasome pathways." (PMID 40784452, 2025). "The ΔretS infection increased cell death, inflammatory factors (IL-1β, IL-6, TNF-α), and reactive oxygen species compared to a T6SS-inactive strain." (PMID 40557319, 2025). "In fact, we previously postulated IL‐1β as a differential cytokine between both groups 1 month after infection." (PMID 39800769, 2025). "Compared with the control group, miR-190a-3p was significantly down-regulated in the infection groups, while IL1B was significantly up-regulated." (PMID 40725488, 2025). "Differentiation of the CD14+ peripheral blood monocytes to macrophages using M-CSF and GM-CSF reduced the influence of TcpC on IL-1β- and TNFα-secretion during an infection with CFT073." (PMID 41310197, 2025). "IL‐1β is a potent pro‐inflammatory cytokine, playing a crucial role in the defense response to host infection and injury." (PMID 39931830, 2025). "When we knocked out C3, we found that inflammatory cytokines such as TNF-α, IL-1β, IL-17A, and IL-6 were upregulated on day 1 post-infection." (PMID 40008883, 2025). "O157:H7 infection elevated IL-1β release in THP-1 cells; however, this effect was reduced when espF was deleted from the O157:H7 strains." (PMID 41522448, 2025). "Prior studies have noted that the accumulation of inflammasome following infection or injury leads to the release of IL-1β and subsequent cell death." (PMID 40075497, 2025). "Infection with P. aeruginosa can not only increase the levels of the proinflammatory cytokines IL-1β, IL-6, and TNF-α but also reduce the expression of the inhibitory cytokine IL-10." (PMID 40270824, 2025). "Compared to the pre‐infection period, the olfactory bulb tissue showed a significant difference in the IL‐1β content on 2 dpi, which was earlier than in the other regions." (PMID 40985474, 2025).
infection (continued). "Human neutrophils produce and release IL-1β during infection, and IL-1β induces directional migration of neutrophils to inflamed sites." (PMID 41316271, 2025). "LINC02528+/– macrophages exhibited significantly upregulated transcriptional and translational levels of IL-1β upon H37Rv infection, while exerting minimal impact on TNF-α and IL-6 expression." (PMID 41433368, 2025). "On the 10th and 14th DPI, the infection with T. evansi induced a significant upregulation of IL-1β and IL-6 mRNA expression levels, whereas mRNA expression levels of TGF-β and IL-10 were downregulated in all infected groups when compared to the CN group." (PMID 40571943, 2025). "For this reason, the expression of the pro-inflammatory cytokines IL-1β, IL-6, and IL-8 and hBDs was analyzed in oral epithelial cells following infection with C. albicans." (PMID 40426561, 2025). "Patients who died from severe COVID exhibit brain‐wide CD8+ T‐cell infiltration, and Long COVID patients show elevated plasma levels of IL‐1β, IL‐6, and TNFα 8–10 months post‐infection." (PMID 40536011, 2025). "RS218 infection triggered robust pyroptotic responses, including increased expression of IL-1β and GSDMD, enhanced GSDMD cleavage to its active N-terminal form, activation of caspase-1 and its cleavage into the p20 subunit, and elevated IL-1β secretion." (PMID 40821830, 2025). "Pre-incubation of THP-1 cells with HepEVs significantly reduced TNF-α, IL-1β, and IL-8 release post-NTHi infection." (PMID 41550953, 2025). "Release of IL-1β during infection with M. kansasii was dependent on NLRP11, similar to the phenotype observed for M. tuberculosis-infected cells." (PMID 40272180, 2025). "Such an effect was confirmed in PA infection, where PA-derived DnaK negatively regulates IL-1β production by cross-talk between JNK and PI3K/PDK1/FoxO1 pathways." (PMID 41164165, 2025). "IL-1β is crucial for the activation and recruitment of immune cells, such as neutrophils and macrophages, to sites of infection or injury to help the body respond to tissue damage." (PMID 39859545, 2025). "The increased levels of TNF-α, IL-1β, and IL-6 promote endothelial activation and leukocyte recruitment to the site of infection, which plays a crucial role in the host’s innate immune defense." (PMID 40564979, 2025). "Abx-treated mice exhibited elevated proinflammatory cytokines (especially IL-1β) in lung and serum after infection, while Dectin-1 knockout mice produced significantly less IL-1β under identical conditions." (PMID 40817809, 2025). "They prevent excessive tissue damage during infection by exhibiting reduced function of important components like caspase-1 and IL-1β, as well as inhibited activation of the NLR family pyrin domain-containing 3 (NLRP3) inflammasome." (PMID 41009960, 2025). "This review examines the role of the P2X7/NLRP3/IL-1β pathway in mediating the effects of infection and neuronal inflammation on brain development." (PMID 40713568, 2025). "In contrast, the number of productively infected cells increased significantly (P < 0.05) for all 3 viruses when exposed to IL1B treatment during or 2 days prior to infection." (PMID 40442100, 2025). "IL-1β was produced by M2-like macrophages, dendritic cells, and neutrophils, whereas M1-like macrophages, which differentiated post-infection, produced IL-23, TNF-α, and IL-6, acting as initiators and amplifiers of the cytokine storm." (PMID 40127923, 2025). "Although brain inflammation was limited in our model, cytokines, including G-CSF, CXCL10, CXCL1, IL-6, and IL-1β, were already increased in the periphery by day 3 post-infection, despite a low to undetectable viral load." (PMID 41472308, 2025). "Cell culture supernatants were collected for an ELISA assay to determine the secreted IL-1β protein levels 16 hr post infection (H)." (PMID 39998486, 2025).
infection (continued). "In the case of H. pylori infection, both IL-1β and IL-17 play crucial roles in pathogenesis; in particular, IL-17 influences the disease outcome upon infection." (PMID 38602383, 2025). "BMDCs stimulated with DNase-treated eggs had markedly reduced IL-1β production, suggesting that DNA from eggs is a major contributor of inflammation during natural infection." (PMID 40100932, 2025). "IL-1β is a primary initiator of innate immune reaction and key player in host defense against infections, while the pro- and anti-inflammatory IL-6 amplifies and modulates inflammatory responses." (PMID 41246354, 2025). "Cell culture supernatants were collected for an ELISA assay to determine the secreted IL-1β protein levels 16 hr post infection (L)." (PMID 39998486, 2025). "At 8 and 24 h of infection, significantly less IL-1β was released from NLRP11−/− macrophages than from WT macrophages." (PMID 40272180, 2025). "At sites of infection or injury, IL-1β promotes the expression of genes involved in inflammation, such as cyclooxygenase-2 (COX-2) and inducible nitric oxide synthase (iNOS), leading to the production of prostaglandin E2 and nitric oxide, respectively." (PMID 40155968, 2025). "The infection activated the upregulation of cytokine expression (il4/13a: 2.6-fold; il4/13b: 5.4-fold), and downregulation of il1b and il8." (PMID 40821846, 2025). "Its knockdown enhances bacterial control, suggesting therapeutic potential; however, translational strategies should be phase-specific: promoting IL-1β activity early in infection while restraining it in chronic disease." (PMID 41433368, 2025). "This reduction in IL-1β release in TbΔirp2-infected cells was reversed upon infection with the complement strain C-TbΔirp2." (PMID 40034497, 2025). "The levels of IL-1β in the two groups were comparable, whereas the level of IL-6 after infection was significantly lower in IFNAR1-/- mice than in WT mice." (PMID 40124358, 2025). "IL-1β is a cytokine released in the early stage of response against infection and initiates pro-inflammatory responses, allowing the synthesis of other cytokines and the activation of different immune cells." (PMID 40509121, 2025). "Adipocyte hypertrophy is linked to an enhanced inflammatory profile.In line with this our findings show that both HIV tropisms increase the LEPTIN/ADIPONECTIN ratio and stimulate IL-1β secretion at 10 days post-infection." (PMID 40746960, 2025). "Accordingly, Tnf expression in whole lung was increased earlier in C57BL/6 mice but reached similar levels by 3 wk after infection, a pattern also observed for the protective cytokine Il1b." (PMID 40986319, 2025). "Animals that survived infection also had transiently increased levels of IL-1β, IFN-γ, IL-15, G-CSF, and IL-2, each of which returned to baseline at ≈10–14 d post-exposure, suggesting regulation of a systemic inflammatory response." (PMID 41460894, 2025). "Interleukin-1B (IL-1B) is a potent pro-inflammatory cytokine essential for host defense responses against infection and injury." (PMID 40778222, 2025). "Our results showed that Acod1 and Il1b were expressed at different timepoints, with IL-1β being expressed in L. major-infected BMDMs at early timepoints, while Acod1 expression occurred later in the course of the infection." (PMID 40142422, 2025). "We show an inverse correlation between the decrease in atRA and the increase in inflammatory cytokines IL‐1β, IL‐6, IL‐10 and IL‐12 in lung tissue during infection." (PMID 40031928, 2025). "As expected, C. albicans induced higher levels of G-CSF, IL-6, IL-1α, and IL-1β than N. glabratus cells in an in vitro OEC infection model." (PMID 40233931, 2025). "On the host side, acute infection triggers proinflammatory cascades involving cytokines like TNFα and IL-1β, along with neutrophil extracellular traps (NETs) to contain the infection." (PMID 40725573, 2025).
infection (continued). "THP‐1 cells in the presence of ROS inhibitors revealed abolished IL‐1β secretion following infection with A/Victoria/3/75 (influenza A)." (PMID 39878363, 2025). "Macrophage IL-1β-driven NF-κB transcription of ACE2 was an important mechanism of dynamic ACE2 upregulation, promoting macrophage susceptibility to infection." (PMID 39763770, 2025). "In rainbow trout, IL-1β upregulation has been documented in the skin (4, 6, and 26 dpi), head kidney (24 h post-infection), hip (6 dpi), and spleen (24 hpi and 26 dpi) (p2)." (PMID 40509043, 2025). "We additionally show that atRA correlates with some inflammatory cytokines across infection types, including IL‐1β, IL‐6, IL‐10 and IL‐12." (PMID 40031928, 2025). "All tested M1 strains induced higher levels of IL-1β than the nigericin control 60 min post-infection, with the exception of SF370." (PMID 39688411, 2025). "IL-1β acts as an endogenous pyrogen, produced and released during the early stages of the immune response to infection, pathology, and stress." (PMID 39940691, 2025). "Accordingly, the eosinophil-activating cytokine IL-5 was elevated in the intestinal samples out to 15 days post-infection, although other inflammatory cytokines investigated (e.g., IL-1β, IL-6, TNF) were unchanged." (PMID 39861887, 2025). "The expression levels of IL-1β were also higher after P. verrucosa infection, but were similar after infection with P. americana and P. submersa." (PMID 40727705, 2025). "In the spleen, Tnf-α was elevated only on day 14 post-infection, while both Il-1β and Il-18 showed a decreasing trend throughout the infection period." (PMID 40892762, 2025). "In vertebrates, including various fish species, IL-1β and IL-8 are key mediators of acute inflammation, coordinating the systemic response to infection and tissue damage, and activating antimicrobial defenses such as lysozyme and other cytokines." (PMID 41463874, 2025). "Three days after H9N2 infection, IL-1β, IL-6, and IL-10 were more significantly increased in all test groups than in the control group (p < 0.05)." (PMID 40218416, 2025). "In humans, the transcription factor p65 is a central transcriptional activator of pro-inflammatory cytokines, including TNF-α, IL-1β, and IL-6, playing pivotal roles in the response to infection, immune cell activation, and inflammatory resolution." (PMID 41141596, 2025). "Consistent with the results of immunoblotting, the secretion of IL-1β was diminished after infection with P. aeruginosa." (PMID 39998486, 2025). "This study delineated the spatiotemporal dynamics of SAA, IL-1β, and IL-6 gene expression during Ich infection." (PMID 40509043, 2025). "We measured the relative mRNA transcripts levels of multiple cytokines generally implicated in inflammation, namely IFNβ, IL1β and TNF in order to decipher any potential differences in the way both cell lines react to MNoV_S99 infection." (PMID 40395509, 2025). "The elevation of IL-6 and IL-1β further supports this, as these cytokines are essential for initiating effective inflammatory responses and recruiting immune cells to sites of infection." (PMID 40969767, 2025). "High-dose infection with all the strains elicited significant increases in GM-CSF, IL-1β, IL-2, IL-4, IL-5, IL-6, and IL-12p70 when compared with the PBS control." (PMID 40333117, 2025). "In this study, after the cellular antioxidant system wasinactivated (6 to 8 h post-infection), the inflammatory cytokines mRNA IL-1β, IL-6, IL-8, and TNF-α further increased and reached the maximum value 8 h post-infection." (PMID 41343264, 2025). "Both in the qPCR and the spatial outcomes, IL-1β had a multifold abundance over IL-1a (10-fold vs 1.5-fold expression during infection)." (PMID 40586608, 2025). "Probiotics also have a negative effect on biofilm formation and modulate the host cell immune response to infection by influencing the balance of pro- and anti-inflammatory cytokines (e.g., IL-8, IL-10, TNFα, IL-1β, and IL-4)." (PMID 41009849, 2025).